ATXN7L3 (ataxin 7 like 3)
Description:
Component of the transcription regulatory histone acetylation (HAT) complex SAGA, a multiprotein complex that activates transcription by remodeling chromatin and mediating histone acetylation and deubiquitination. Within the SAGA complex, participates in a subcomplex that specifically deubiquitinates both histones H2A and H2B. The SAGA complex is recruited to specific gene promoters by activators such as MYC, where it is required for transcription. Required for nuclear receptor-mediated transactivation. Within the complex, it is required to recruit USP22 and ENY2 into the SAGA complex. Regulates H2B monoubiquitination (H2Bub1) levels. Affects subcellular distribution of ENY2, USP22 and ATXN7L3B.
Synonyms: DKFZp761G2113; HATONS; SGF11
Tractability: Antibody: the Human Protein Atlas places it where antibodies can reach.
Gene: Protein-coding gene on chromosome 17 (44,191,805 to 44,200,961, reverse strand). Ensembl gene ENSG00000087152.
Subcellular location: Nucleus
Subcellular location (Human Protein Atlas): Nuclear speckles; Plasma membrane
Pathways (Reactome):
Chromatin organization: HATs acetylate histones
Gene Ontology:
Molecular function: protein binding; transcription coactivator activity; zinc ion binding
Biological process: positive regulation of DNA-templated transcription; regulation of transcription by RNA polymerase II; regulation of DNA repair; regulation of RNA splicing
Cellular component: DUBm complex; nucleus; SAGA complex; transcription factor TFTC complex; SAGA-type complex
Genetic constraint (gnomAD): Loss-of-function variants: 6 observed, 52.09 expected, observed/expected ratio (o/e) 0.12, 90% interval 0.062 to 0.23. The upper end of that interval is the gene's LOEUF score, 0.23, which puts it in group 1 of 6, group 1 being the genes least tolerant of losing a copy. Missense variants: 322 observed, 466.63 expected, observed/expected ratio (o/e) 0.69, 90% interval 0.63 to 0.76. Synonymous variants: 198 observed, 173.32 expected, observed/expected ratio (o/e) 1.14, 90% interval 1.02 to 1.28.
Homologues: Orthologues: chimpanzee ATXN7L3 (100% identical), macaque ATXN7L3 (100% identical), mouse Atxn7l3 (99% identical), rabbit ATXN7L3 (99% identical), pig ATXN7L3 (99% identical), dog ATXN7L3 (99% identical), rat Atxn7l3 (99% identical), guinea pig ATXN7L3 (93% identical), tropical clawed frog atxn7l3 (76% identical), zebrafish atxn7l3a (73% identical). Paralogues in human: ATXN7 (24% identical), ATXN7L2 (23% identical), ATXN7L1 (22% identical), ATXN7L3B (15% identical).
Diseases named in the same sentence as ATXN7L3 in open-access papers:
ATXN7L3 is named in the same sentence as 8 diseases in open-access papers, as found by Europe PMC text mining. Sharing a sentence is not in itself a finding about the gene and the disease. The quoted sentences say what the papers report.
cervical cancer (2 papers, 2020 to 2021). A primary or metastatic malignant neoplasm involving the cervix. "In cervical cancer, miR-877-5p acts as a downstream target of long non-coding RNA DSCAM-AS1, and DSCAM-AS1 plays a vital role in the tumorigenesis via miR-877-5p/ATXN7L3 axis in cervical cancer." (PMID 34124974, 2021).
cancer (4 papers, 2017 to 2021). A tumor composed of atypical neoplastic, often pleomorphic cells that invade other tissues. "Previous study has indicated that ATXN7L3 exerts an important influence on cancer development." (PMID 31737900, 2020). "Interestingly, both Usp22 and ATXN7L3, a Usp22 interacting partner required for its enzymatic activity, are shown to be co-recruited with ER to different promoters and regulate the expression levels of downstream targets in cancer cell lines." (PMID 34503086, 2021).
tumor (2 papers, 2020 to 2025). "In outline, our work corroborated that DSCAM-AS1 facilitates the tumor growth of CC by targeting miR-877-5p/ATXN7L3 axis, which could deliver unbelievable methods for CC treatment." (PMID 31737900, 2020). "For example, ATXN7L3 and ENY2 stimulate activity of multiple H2B deubiquitinases that play a key role in cellular proliferation and tumor growth." (PMID 31737900, 2020). "However, whether ATXN7L3 can promote tumor development in CC is undiscovered yet." (PMID 31737900, 2020).
ATXN7L3 also shares sentences with these, for which no sentence is quoted: infectious disease (1 paper); mental retardation (1); metabolic disorder (1); neurological disorders (1); retinal degeneration (1).